TNFSF18 (TNF superfamily member 18)
Description:
Cytokine that binds to TNFRSF18/AITR/GITR. Regulates T-cell responses. Can function as costimulator and lower the threshold for T-cell activation and T-cell proliferation. Important for interactions between activated T-lymphocytes and endothelial cells. Mediates activation of NF-kappa-B. Triggers increased phosphorylation of STAT1 and up-regulates expression of VCAM1 and ICAM1. Promotes leukocyte adhesion to endothelial cells. Regulates migration of monocytes from the splenic reservoir to sites of inflammation (By similarity).
Synonyms: AITRL; hGITRL; GITRL; TL6; TNLG2A
Tractability: Small molecule: it has a high-quality binding pocket. Antibody: UniProt places it where antibodies can reach, with high confidence; its Gene Ontology location is reachable by antibodies, with high confidence; UniProt predicts a signal peptide or a membrane-spanning region.
Gene: Protein-coding gene on chromosome 1 (173,039,202 to 173,050,941, reverse strand). Ensembl gene ENSG00000120337.
Subcellular location: Cell membrane
Pathways (Reactome):
Immune System: TNFs bind their physiological receptors
Gene Ontology:
Molecular function: identical protein binding; protein binding; signaling receptor binding; tumor necrosis factor receptor superfamily binding; tumor necrosis factor receptor binding
Biological process: positive regulation of cell adhesion; positive regulation of leukocyte migration; positive regulation of tyrosine phosphorylation of STAT protein; cell-cell signaling; negative regulation of apoptotic process; regulation of T cell proliferation; signal transduction; T cell proliferation involved in immune response; tumor necrosis factor-mediated signaling pathway; immune response; negative regulation of T-helper 17 cell lineage commitment; positive regulation of inflammatory response; positive regulation of macrophage chemotaxis; positive regulation of monocyte chemotaxis; regulation of dendritic cell chemotaxis; regulation of protein-containing complex assembly
Cellular component: cell surface; plasma membrane; membrane
Genetic constraint (gnomAD): Loss-of-function variants: 5 observed, 7.9 expected, observed/expected ratio (o/e) 0.63, 90% interval 0.33 to 1.32. That is too few expected variants to judge how well the gene tolerates losing a copy. Missense variants: 199 observed, 197.18 expected, observed/expected ratio (o/e) 1.01, 90% interval 0.9 to 1.13. Synonymous variants: 67 observed, 73.38 expected, observed/expected ratio (o/e) 0.91, 90% interval 0.75 to 1.12.
Homologues: Orthologues: chimpanzee TNFSF18 (100% identical), macaque TNFSF18 (97% identical), dog TNFSF18 (73% identical), pig TNFSF18 (73% identical), rabbit TNFSF18 (71% identical), guinea pig TNFSF18 (61% identical), rat Tnfsf18 (54% identical), mouse Tnfsf18 (50% identical).
Diseases named in the same sentence as TNFSF18 in open-access papers:
TNFSF18 is named in the same sentence as 92 diseases in open-access papers, as found by Europe PMC text mining. Sharing a sentence is not in itself a finding about the gene and the disease. The quoted sentences say what the papers report.
breast carcinoma (10 papers, 2020 to 2023). "Specifically, CD112, TNFSF4, TNFSF18, and LGALS9 were significantly overexpressed in breast carcinomas, strongly suggesting potent and valuable effects." (PMID 34545132, 2021). "Furthermore, PD-L1, CD112, TNFRSF14, TNFSF4, TNFSF18, CD48, and LGALS9 were analyzed for abnormal expression patterns in breast carcinomas." (PMID 34545132, 2021).
asthma (5 papers, 2020 to 2025). "TNFSF8/TNFSF15 and TNFSF13 loci are also associated with the risk of IgA nephropathy, while TNFSF4/TNFSF18 locus has previously been associated with the risk of eczema, asthma and narcolepsy, all with concordant effects to IgA levels." (PMID 36369178, 2022).
gastric cancer (3 papers, 2022 to 2025). A primary or metastatic malignant neoplasm involving the stomach. "Then, we chose three genes (CXCR4, TNFSF18, and TAP1) that were all linked to the length of survival for patients with stomach cancer." (PMID 35509844, 2022).
colon carcinoma (2 papers, 2019 to 2024). "DDX58, XAF1, OAS1, IFI27, IFI44 or IFIT3 was indeed downregulated and CHST4 or TNFSF18 was upregulated in MDM4 overexpressed colon cancer cells." (PMID 38281029, 2024). "We selected eight representative immune-related molecules for qPCR validation in SW480 and another colon cancer cell line HT29: DDX58, CHST4, TNFSF18, XAF1, OAS1, IFI27, IFI44, IFIT3." (PMID 38281029, 2024).
esophageal squamous cell carcinoma (1 paper, 2025). Esophageal squamous cell carcinoma (ESCC) is a type of esophageal carcinoma (EC) that can affect any part of the esophagus, but is usually located in the upper or middle third. "In this study, we selected PSD3, CD274, and TNFSF18 for integrated analysis based on a combination of transcriptomic screening, immunological relevance, and prognostic associations in esophageal squamous cell carcinoma (ESCC)." (PMID 40895529, 2025). "In this study, we investigated PSD3, CD274 (PD-L1), and TNFSF18 as potential immune-related biomarkers in esophageal squamous cell carcinoma (ESCC) using integrative transcriptomic and experimental approaches." (PMID 40895529, 2025).
Lymphatic Metastasis (1 paper, 2021). Transfer of a neoplasm from its primary site to lymph nodes or to distant parts of the body by way of the lymphatic system. "The expression levels of RELT, TNFSF18, and TNFRSF25 were high, and the expression levels of EDA2R were low in patients with lymphatic metastasis." (PMID 34484286, 2021).
osteosarcoma (1 paper, 2022). A usually aggressive malignant bone-forming mesenchymal neoplasm, predominantly affecting adolescents and young adults. "The result indicated that CCL28, KLF2 and TNFSF18 did not significantly affect cell apoptosis, while the knockdown of HMGB1 and TLR4 significantly increased the proportion of apoptotic of osteosarcoma cells." (PMID 36204682, 2022).
silicosis (1 paper, 2025). Silicosis is a respiratory disease caused by breathing in (inhaling) silica dust. "In addition, Lilr4a, Lilr4b, and Tnfsf18 were significantly up-regulated in the early and middle stages of silicosis, while Pdcd1, Ctla4, and Tigit were significantly up-regulated in the middle and late stages of silicosis." (PMID 39498466, 2025).
tumor (76 papers, 2009 to 2026). "In addition to prognostic relevance, our ROC curve analyses showed that PSD3, CD274, and TNFSF18 exhibit moderate to high diagnostic accuracy in distinguishing tumor tissues from normal controls." (PMID 40895529, 2025). "The first major finding of our study is the consistently elevated expression of CD274 and TNFSF18 in ESCC tumor tissues compared to normal esophageal epithelium, as observed in both the TCGA and GEO datasets." (PMID 40895529, 2025). "CD274 and TNFSF18 were consistently up-regulated in tumor tissues across both TCGA and GEO cohorts, whereas PSD3 exhibited a context-dependent pattern, showing significant up-regulation in TCGA but no differential expression in GEO." (PMID 40895529, 2025). "This integrated approach enables a more comprehensive understanding of PSD3, CD274, and TNFSF18 in the context of the ESCC tumor immune microenvironment." (PMID 40895529, 2025). "TNFSF18, a member of the tumor necrosis factor superfamily known to modulate T cell activity, was selected based on its emerging links to tumor immunity and its co-regulation patterns with PSD3." (PMID 40895529, 2025). "To establish a foundational understanding of PSD3, CD274 (PD-L1), and TNFSF18 expression in cancer, we first conducted a comparative analysis of their mRNA levels across a wide array of tumor types using The Cancer Genome Atlas (TCGA) datasets." (PMID 40895529, 2025). "Given the immunomodulatory roles of CD274 and TNFSF18, along with the emerging relevance of PSD3 in cancer biology, we next investigated their associations with tumor-infiltrating immune cells using immune deconvolution data from the GEO dataset GEO dataset." (PMID 40895529, 2025). "The natural ligand for GITR (GITRL, also known as TNFSF18) is mainly expressed on activated APCs and has been observed in specific tumor types." (PMID 39684559, 2024). "The expression of HMGB1 and TLR4 was significantly high in tumor tissue compared with that in normal tissue, the expression of CCL28, KLF2 and TNFSF18 in tumor were similar to normal tissues." (PMID 36204682, 2022). "Further dissection of immune cell-type correlations provided additional insight into how PSD3, CD274, and TNFSF18 may shape the tumor immune microenvironment (TME) in ESCC." (PMID 40895529, 2025). "CD36 also exhibited positive correlations with several immunostimulators, including C10orf54, CXCL12, ENTPD1, CD28, and TNFSF18, suggesting that it may contribute to immune activation pathways and modulation of antitumor immune responses in the tumor microenvironment." (PMID 41550652, 2025). "For example, increased immune infiltration associated with high gene expression might not be causally mediated by PSD3, CD274, or TNFSF18, but rather reflect a broader inflammatory state of the tumor." (PMID 40895529, 2025). "These distinct enrichment profiles underscore the divergent functional landscapes of these genes: PSD3 appears to drive tumor-intrinsic processes, while CD274 and TNFSF18 modulate tumor-immune interactions." (PMID 40895529, 2025). "Expression of four genes decreased after CaPa, TNFSF18, coding for GITRL, HMGB1, TNFSF4, coding for OX-40 L and HLA-A, all involved in the positive regulation of anti-tumor immune response." (PMID 38581044, 2024). "NLRP1 is also significantly associated with most immune‐stimulating genes except for CD276, HHLA2, NTSE, PVR, TNFSF18 and UNBP1 in the HNSC‐excluded tumours." (PMID 39318060, 2024). "We demonstrated that P4HA1 expression was positively correlated with the expression of TNFSF15, CD80, VTCN1, TNFSF18, and CD200R1 in multiple tumor types but negatively correlated with the expression of CD40LG and CD244." (PMID 35812752, 2022). "We and others demonstrated that tumor-educated platelets (TEP) can express a manifold of tumor necrosis factor superfamily members including LIGHT (TNFSF14), GITRL (TNFSF18), OX40L some of which are known immune checkpoint molecules." (PMID 33816291, 2021).
tumor (continued). "The TNFR superfamily proteins are expressed by antigen-presenting cells (APC) or tumor cells, including TNFSF4 (OX40L), TNFRSF5 (CD40), TNFSF7 (CD70), TNFSF9 (CD137L), TNFRSF14 (HVEM), and TNFSF18 (GITRL)." (PMID 30609841, 2019). "However, other genes regulation involved in anti-tumor immune response and resistance to immunotherapies, NECTIN4, HMGB1, TNFSF18, by CaPa or CaGe seem to be dependent on the cell line used and thus to be more heterogeneous." (PMID 38581044, 2024). "RELT and TNFSF10 had high expression levels in tumor tissues compared with normal tissues, while EDA2R and TNFSF18 had low expression levels in tumor tissues compared with normal tissues in TCGA dataset." (PMID 34484286, 2021). "TNFSF18 (GITRL) could mediate NK cell activity and may influence anti-tumor immunity." (PMID 36676763, 2023). "TNFSF18 is involved in the functional regulation of immune cells in tumors, especially T cells, B cells, macrophages and dendritic cells, while it has low or no expression in tumor cells." (PMID 36899380, 2023). "Interestingly, despite their central roles in anti-tumor immunity, our in silico analyses did not reveal significant correlations between the expression of PSD3, CD274, or TNFSF18 and the infiltration of CD8+T cells or natural killer (NK) cells." (PMID 40895529, 2025).
cancer (30 papers, 2010 to 2025). A tumor composed of atypical neoplastic, often pleomorphic cells that invade other tissues. "In contrast, a uniform negative association with PEBP1/STK11 co-expression was found in most of the genes encoding TNF ligands (ENFSF13B, TNFSF4, TNFSF9, TNFSF14, TNFSF18, and TNFSF15) in almost all cancer types." (PMID 40806276, 2025). "Also, we observed that USP5 was correlated with most immune inhibitors and immune stimulators except for KIR2DL1, KIR2DL3 and TNFSF18 in pan-cancer." (PMID 37268697, 2023). "Lastly, while CD274 and TNFSF18 are well-characterized in immune signaling, PSD3’s role in cancer remains poorly defined and should be interpreted with caution." (PMID 40895529, 2025).
infection (18 papers, 2010 to 2025). The state of being infected such as from the introduction of a foreign agent such as serum, vaccine, antigenic substance or organism. "In mice, the resolution of infection was also associated specifically with a strong expression of Tnfsf18 (glucocorticoid-induced TNF-related ligand [GITRL]), confirmed by flow cytometry." (PMID 31533045, 2019). "TNFSF13B contributes to the activation, proliferation, and differentiation of B lymphocytes, while TNFSF18 regulates the activation of monocytes and T lymphocytes in the immune response against pathogen infection." (PMID 38847223, 2024). "These included cytokines and cytokine receptors (Il11, Tnfsf18, and Ackr4), genes involved in infection (Ptgs2 and Heyl), cell adhesion and migration (Spon2 and Mmp10)." (PMID 35293863, 2022). "After the resolution of infection, Tnfsf18 (GITRL) is the most strongly upregulated cytokine." (PMID 31533045, 2019). "Based on the RNA-seq analysis, we observed that in non-decidualized spheroids, infection led to an increased fold change expression of TNFSF18 and LEFTY1." (PMID 39666439, 2025).
TNFSF18 also shares sentences with these, for which no sentence is quoted: autoimmune disease (8 papers); Primary Sjögren’s Syndrome (6); Arthritis (5); atherosclerosis (4); glioma (4); Hashimoto thyroiditis (4); lung carcinoma (4); Autoimmunity (3); diabetes (3); melanoma (3); rheumatoid arthritis (3); systemic lupus erythematosus (3); viral infection (3); autoimmune thyroid disease (2); epithelioid mesothelioma (2); gastric tumor (2); infectious disease (2); inflammation (2); mesothelioma (2); Sepsis (2); vasculitis (2); acute myeloid leukemia (1); airway hyperresponsiveness (1); allergic asthma (1); Allergy (1); alopecia (1); anemia (1); autoimmune type 1 diabetes (1); bacterial infection (1); bladder cancer (1).
A further 51 diseases each share a sentence with TNFSF18 in 1 paper.